MMP13 (matrix metallopeptidase 13)
Diseases named in the same sentence as MMP13 in open-access papers (continued):
Sharing a sentence is not in itself a finding about the gene and the disease.
breast carcinoma (continued). "However, expression of MMP13 rescued the inhibition of breast cancer invasion associated with RKIP expression in vitro." (PMID 26308852, 2015). "Combined with the lack of any apparent adverse tumor promotion due to MMP13 deficiency in MMP13-null mice, MMP13 may represent a new therapeutic target in breast cancer." (PMID 22253746, 2012). "Finally, ETV4 and MMP13 co-overexpression is associated with poor prognosis in breast cancer." (PMID 29996935, 2018). "It is unknown what induces Mmp13 in the breast carcinoma-associated myofibroblasts, but the restricted expression of Mmp13 in dense fibrous stromal septae within the central parts of the invasive MMTV-PyMT tumors suggests a locally expressed tumor-cell derived factor." (PMID 18698413, 2008). "The combination of unique proteolytic capabilities, network centrality, and subtype-specific duality positions MMP13 as a critical node in breast cancer progression." (PMID 40243781, 2025). "Despite extensive research on breast cancer biology, the functional implications of MMP13 in relation to the physical properties of breast tumours remain unexplored in the existing literature." (PMID 40243781, 2025). "In breast cancer, MMP13 can be secreted by CAFs and the primary tumour, also promoting BM degradation and tumour cell migration." (PMID 40243781, 2025). "The anti‐breast cancer mechanism of Codonolactone is associated with the inhibition of the activity and expression of matrix metalloproteinases (MMP‐9 and MMP‐13)." (PMID 40008240, 2025). "While MMP13 promotes the EMT, breast cancer cells produce more MMP13 during an EMT, therefore creating positive feedback." (PMID 40243781, 2025). "MMP13 exhibits unique characteristics that make it particularly relevant in the context of breast cancer." (PMID 40243781, 2025). "In contrast, M1 TAMs, which are considered tumour-suppressive, secrete MMP13 and exert anti-stiffness effects in breast cancer." (PMID 40243781, 2025). "By downregulating the activity of the Runx2 transcription factor and restraining the binding of Runx2 to the MMP‐13 promoter sequence, it exhibits anti‐breast cancer activity." (PMID 40008240, 2025). "As a potential target, MMP13 has been proven to act as a downstream target to inhibit breast cancer." (PMID 40243781, 2025). "In this review, the recent advances made in understanding the roles of MMP13 in regulating the physical properties of breast cancer regarding stiffness, plasticity, viscoelasticity, collagen alignment, and temperature have been discussed." (PMID 40243781, 2025). "Matrix metalloproteinase 13 (MMP13) is an important marker of breast cancer and plays important roles in matrix remodelling and cell metastasis." (PMID 40243781, 2025). "The observed differences in outcomes between the inhibitory effects of MMP13 on breast cancer lung metastasis in mouse models and its promotion of metastasis in human breast cancer warrant further investigation." (PMID 40243781, 2025). "Intriguingly, MMP13 exhibits context-dependent mechanomodulatory effects, demonstrating anti-fibrotic activity and inhibiting the metastasis of breast cancer." (PMID 40243781, 2025). "At the same time, angiogenesis and increased metabolism are important mechanisms through which MMP13 promotes a temperature increase in breast cancer." (PMID 40243781, 2025). "Emerging evidence has demonstrated that MMP13 can simultaneously induce matrix stiffening and fluidisation—a dual regulatory mechanism that critically influences breast cancer cell invasion and migration." (PMID 40243781, 2025). "Bones-bearing breast cancer cells exhibited a higher prevalence of p16Ink4a+, senescence-associated distension of satellites (SADS)+, and MMP13+ osteocytes." (PMID 38558984, 2024). "Our in vivo and in vitro studies support that, in the context of breast cancer, senescent osteocytes have increased osteoclastogenic potential (increased Rankl, Mmp13, Il6) and are key drivers of cancer-induced bone resorption." (PMID 38558984, 2024).
breast carcinoma (continued). "FOXO3a promoted invasive migration by inducing the expression of matrix metalloproteinase 9 (MMP-9) and MMP-13, whereas depletion of FOXO3a in breast cancer cells leads to decreased tumor size specifically due to attenuated invasive migration." (PMID 38714753, 2024). "Treatment with the senolytic drugs Dasatinib + Quercetin (DQ) prevented or reduced the increased expression of p16Ink4a, Mmp13, and Il6, supporting a direct link between the changes in gene expression and the cellular senescence induced by breast cancer cells." (PMID 38558984, 2024). "Treatment with breast cancer CM or direct co-culture with breast cancer cells upregulated Rankl, Mmp13, and Il6 and decreased Cthrc1 mRNA expression in MLO and Ocy454 cells." (PMID 38558984, 2024). "LINC00511 promotes breast cancer proliferation, migration, and invasion through the miR-150/MMP13 axis." (PMID 37758759, 2023). "Here, we identify MMP13 as a key protease in facilitating the progression of early stage breast cancer, with significantly reduced invasion observed upon inhibition or knockdown of myoepithelial-MMP13 across 3D models." (PMID 36864079, 2023). "It has been shown that MMP‐13 is overexpressed during the cancer metastasis process in various tumour cells, including breast cancer, colorectal cancer, papillary thyroid carcinoma, laryngeal cancer and head and neck cancer." (PMID 37710409, 2023). "MMP-13 is secreted by breast cancer cells following stimulation by osteoblasts or inflammatory mediators, including IL-8." (PMID 38138968, 2023). "Evidence about Mmp-13 in breast cancer-induced osteolysis indicates this Mmp as a promising therapeutic target for breast cancer bone metastasis, where also Myb is involved as well." (PMID 37701782, 2023). "In vivo, mouse studies have shown that MMP-13, a “classic collagenase” almost universally upregulated across malignancies, promotes mammary tumor-induced osteolysis by activating MMP-9 and increasing TGF-β signaling at the tumor-bone interface." (PMID 37266453, 2023). "Soluble factors, such as IL-6, produced by breast cancer cells induce MMP-13 expression in osteoblasts." (PMID 35805035, 2022). "MMP13 has significantly increased expression in breast cancer tissue and is predicted to play a significant role in tumor invasion and metastasis." (PMID 36106139, 2022). "MMP-13 is believed to be the primary protease to degrade type I collagen and aids breast cancer bone metastasis." (PMID 35805035, 2022). "The inhibition of MMP-13 expression in breast cancer cells at the tumour–bone interface significantly reduced TGF-β signalling, leading to a decrease in tumour-induced osteolysis." (PMID 35805035, 2022). "MMP-13 overexpression in cancer was first reported in breast cancer and has subsequently been observed in many other cancers, such as colorectal, prostate, oesophageal, thyroid and gastric cancers, as well as multiple myeloma (MM)." (PMID 35805035, 2022). "For example, the binding of ETS variant transcription factor 4 (ETV4) to the AP-1 binding site in the MMP-13 promoter region induced MMP-13 expression in breast cancer." (PMID 35805035, 2022). "The authors suggest reduced expression of Runx2 and related target genes, including IL-11, MMP13, and PThrP, in breast cancer cells in the presence of miR-135 and miR-203 as a working mechanism." (PMID 35158995, 2022). "The conclusion of previous research was that MMP-13 is involved in osteoclast differentiation but also in breast cancer and bone metastases." (PMID 35163727, 2022). "In response to the AR agonist CI-4AS-1, the expression of miR-100 and miR-125 was significantly reduced in MDA-MB-453 breast cancer cells, leading to the increased expression of miR-100 and miR-125 target metalloprotease-13 (MMP13)." (PMID 35163477, 2022).
breast carcinoma (continued). "TNIK is required for JNK1 activation, a kinase that activates the AP-1 complex, whereas MMP13, a metalloprotease, that is regulated through the same signalling pathway, is considered as a marker of breast cancer invasiveness." (PMID 34403459, 2021). "The c-Jun/ATF-3 complex can bind to the matrix metalloproteinase (MMP-13) promoter AP-1 to regulate the invasion of breast cancer cells." (PMID 34787047, 2021). "Lastly, we show that ABL expression in highly metastatic breast cancer MDA-MB231 cells is associated with their invasive capacity and that ABL-mediated invasion is abolished by depletion of endogenous RUNX2 or MMP13." (PMID 34136397, 2021). "In conclusion, our study is the first to establish that sauchinone suppresses the proliferation and invasion of metastatic breast cancer cells by inhibiting MMP13 expression." (PMID 34643237, 2021). "To explore the mechanisms underlying the regulation of migration and invasion in breast cancer cells following sauchinone treatment, we first screened representative MMPs (MMP2, MMP3, MMP9, and MMP13) via immunoblotting analysis." (PMID 34643237, 2021). "This ABL–RUNX2 interaction is necessary for the transcriptional induction of a major determinant of invasion in breast cancer, MMP13 (also known as collagenase-3)." (PMID 34831147, 2021). "MMP13 was involved in breast cancer progression induced by ETV4 transcription factor, Golgi membrane protein 1, and gremlin-1 (GREM1)." (PMID 34643237, 2021). "Lastly, we found that ABL expression in highly metastatic breast cancer MDA-MB231 cells is associated with their invasive capacity and that ABL-mediated invasion is abolished by depletion of endogenous RUNX2 or MMP13." (PMID 34136397, 2021). "ABL-RUNX2 complex formation is required for expression of its target gene MMP13 and subsequent invasive capacity in metastatic breast cancer cells." (PMID 34136397, 2021). "Sauchinone treatment inhibited MMP13 expression by down-regulating Akt-CREB signaling pathway in breast cancer cells." (PMID 34643237, 2021). "In this study, we also identified MMP13 as a new molecular target for sauchinone’s efficacy in inhibiting breast cancer cell growth, migration, and invasion." (PMID 34643237, 2021). "The results of this study revealed that MMP-13 protein expression level in breast cancer tissues was significantly higher than benign breast tissues." (PMID 34452576, 2021). "Mouse MMP-13 is markedly upregulated in the stroma during tumor growth and the progression of breast cancer." (PMID 34072157, 2021). "Expression of MMP-13 has been detected in various types of cancers, including papillary thyroid carcinoma, colorectal, and breast cancers." (PMID 34452576, 2021). "The aim of this study was to evaluate the expression and prognostic value of MMP-13 tissue distribution pattern in human breast cancer compared to benign breast lesions." (PMID 34452576, 2021). "In particular, MMP13 has been reported to promote the metastasis of breast cancer cells to organs such as bones and lungs." (PMID 34643237, 2021). "Some studies demonstrated that golgi somal membrane protein 1 (GOLM1) promoted the proliferation and metastasis of breast cancer cells by regulating matrix metalloproteinase-13 (MMP13)." (PMID 35127514, 2021). "MMP13 is one of the secreted proteins overexpressed in breast cancer tissues compared with normal adjacent tissues." (PMID 34643237, 2021). "The extract of Urtica dioica, a perennial herb, inhibited breast cancer cell migration by regulating microRNA-21 and several MMPs including MMP13." (PMID 34643237, 2021). "In summary, ATF3 can upregulate genes involved in breast cancer cell metastasis, including MMP13, FN, TWIST1, Slug, and Snail, in MCF10CA1a cells." (PMID 32922364, 2020). "Knockdown of ATF-3 expression in MDA-MB231 breast cancer cells decreases cell number, cell migration, and the expression levels of invasive and metastatic genes, such as MMP-13 and Runt-related transcription factor 2 (Runx2)." (PMID 32922364, 2020).
breast carcinoma (continued). "MMP-2, MMP-9 and MMP-13 are also reported to be overexpressed in breast cancer patients and correlated with more aggressive phenotypes of breast cancer, poor prognosis and decreased life expectancy." (PMID 32586313, 2020). "MMP13 knockdown markedly inhibited lung metastasis of breast cancer MCF-7 cells overexpressing Pit-1." (PMID 33287358, 2020). "Of various MMPs, MMP13 was first identified in breast cancer and has since been reported in other types of cancer." (PMID 33287358, 2020). "FOXO3 promotes breast cancer cell invasion through the induction of MMP-9 and MMP-13 and has further been associated with MMP-9 activity and elevated invasion capacity in glioma, and with increased cell migration and invasion in gastric and colorectal cancer." (PMID 31861249, 2019). "Consistent with this, we found that, in breast cancer cells, both MMP13 and MMP9 were upregulated by Osx, suggesting that Osx has a function in invasion, an initial stage in the metastasis cascade." (PMID 30631043, 2019). "The negative effect of miR-140 on MMP9 has been reported to inhibit breast cancer invasion, while estrogen has been shown to suppress MMP13 expression through the upregulation of miR-140 in the development of menopausal arthritis." (PMID 31915516, 2019). "Overexpressing LPP1 also decreased mRNA levels of MMP-1, MMP-3 and MMP-13 in BT-549 breast cancer cells and 4T1 mouse breast cancer cells." (PMID 31534541, 2019). "FOXO3 promotes cell invasion through the induction of the matrix metalloproteinases MMP-9 and MMP-13 in breast cancer cells." (PMID 31861249, 2019). "MMP9 and MMP13 is up-regulated in breast cancer tissue, and were involved in bone metastasis of tumor progression." (PMID 30918839, 2019). "Consistently, functional evidence demonstrates that MMP13 increases the invasive capacities of the malignant cells in breast cancer." (PMID 29996935, 2018). "Nevertheless, MMP13 was first identified in a breast tumor library, and an increasing amount of data demonstrates its role in tumorigenesis and particularly in breast cancer." (PMID 29996935, 2018). "Induction of an EMT program in breast cancer cells causes MMP production, and increased expression of MMP3, MMP10, and MMP13 was observed upon TGF-β stimulation of human breast cancer cell lines." (PMID 30356678, 2018). "Altogether, these results show that MMP13 acts as a relay of ETV4 to control mammary cancer cells’ tumorigenic abilities." (PMID 29996935, 2018). "Given that MMPs are key actors of the tumorigenic and metastatic processes, we evaluated the influence of MMP13 on phenotypic modification of mammary cancer cells and in a context of ETV4 overexpression." (PMID 29996935, 2018). "We next explored the action of dasatinib on NRG‐induced upregulation of MMP13 levels using several cell lines belonging to different breast cancer subtypes." (PMID 29032615, 2017). "Here, we show that dasatinib restricted NRG‐induced MMP13 upregulation, both in vitro and in vivo, and in vivo metastatic dissemination of breast cancer cells." (PMID 29032615, 2017). "The finding with respect to gender difference is interesting because MMP‐13 was originally detected from breast cancer samples." (PMID 29744196, 2017). "In summary, in the current study, we have shown that dasatinib restricts NRG‐induced MMP13 upregulation and metastatic dissemination of breast cancer cells." (PMID 29032615, 2017). "Here, we show that dasatinib, a small tyrosine kinase inhibitor with intermediate selectivity, restricts MMP13 upregulation and metastatic dissemination of breast cancer cells once the NRG–HER signaling axis is activated." (PMID 29032615, 2017). "SNHG12 was also clarified to promote cell migration by regulating MMP13 expression in breast cancer." (PMID 29137407, 2017). "Co-expression of MMP13 antagonized RKIP- mediated suppression of breast cancer cell invasion in vitro." (PMID 26308852, 2015).
breast carcinoma (continued). "Here we show that in breast cancer the expression of RKIP also negatively correlates with the expression of MMP13." (PMID 26308852, 2015). "We tested the association between the MMP13 expression and SED in an independent cohort of 52 breast cancer patients by qRT-PCR using fresh tissues obtained from the curative surgeries." (PMID 26669540, 2015). "Both ANGPTL2 and CXCR4 expression levels were positively correlated with high MMP-13 expression in breast cancer patient specimens." (PMID 25773070, 2015). "Tumor-derived MMP-13 correlates with aggressive tumor phenotypes, and inversely correlated with the overall survival of breast cancer patients." (PMID 25609201, 2015). "Human MMP-13, also known as collagenase-3, is a matrix metalloproteinase originally identified in breast carcinomas." (PMID 25948792, 2015). "MMP-9 and MMP-13 are under the direct control of RUNX2 in a number of cell types, including breast cancer cells, and this was associated with invasive behavior of cancer cells." (PMID 26404249, 2015). "We also establish that RKIP inhibits breast cancer invasion by suppressing MMP13 both in vitro as well as in an in vivo mouse transplantation model." (PMID 26308852, 2015). "A possible explanation is that tumor cells stimulate the production of MMP-13 in adjacent cells, as high levels of MMP-13 mRNA were observed in stromal cells adjacent to MCF-7 breast cancer cells in vitro." (PMID 25664615, 2015). "RKIP expression inhibits MMP13 promoter driven luciferase reporter activities in cycling breast cancer cells." (PMID 26308852, 2015). "Recently, the expression of MMP13 was evaluated in a cohort of 263 breast cancer patients by immunohistochemistry staining." (PMID 26308852, 2015). "In response to TGFβ, RUNX2 interacts with SMAD3 and JUNB at the distal runt domain (RD) site of the MMP13 (collagenase-3) promoter in MDA-MB-231 breast cancer cells." (PMID 26204939, 2015). "To examine if RKIP’s expression also reversely correlates with that of MMP13 in vivo, we interrogated publicly available DNA microarray expression datasets derived from human breast cancer samples." (PMID 26308852, 2015). "To summarize, we have established MMP13, which plays a crucial role in breast cancer invasion, as a novel molecular target of RKIP." (PMID 26308852, 2015). "Although it was shown that ectopic expression of RKIP suppressed the MMP13 expression in MDA-MB231 breast cancer cells, the clinical relevance and biological consequences of the MMP13 inhibition in breast cancer by RKIP remain to be determined." (PMID 26308852, 2015). "It has been established earlier that tumor-derived MMP13 correlates with aggressive breast cancer phenotypes and inversely correlates with the overall patient survival." (PMID 26308852, 2015). "Restoration of RKIP in low-RKIP-expressing 4T1 cells suppresses MMP13 expression and inhibits breast cancer cell invasion in vitro and breast cancer metastasis in a mouse model." (PMID 26308852, 2015). "MMP-13 abrogation was demonstrated to reduce breast cancer metastases by inhibiting osteoclast cells' differentiation or decreasing stromal MMP-13 expression." (PMID 26528698, 2015). "The study concluded that tumor-derived MMP13 correlated with aggressive breast cancer phenotypes and inversely correlated with the overall patients’ survival." (PMID 26308852, 2015). "For example, previous studies have shown pro-tumorigenic and pro-metastatic role of ERBB2, WNT7b, S100A7, and MMP13 in breast cancer." (PMID 26669540, 2015). "In this study we found that Pit-1 regulated MMP-1 and MMP-13 in breast cancer cells at transcriptional level." (PMID 25527274, 2014). "In the present study we also found positive correlations between global expression (score values) of Pit-1 and either MMP-1 or MMP-13 expression in human primary breast carcinomas." (PMID 25527274, 2014).